SETD1B (SET domain containing 1B, histone lysine methyltransferase)
Description:
Histone methyltransferase that catalyzes methyl group transfer from S-adenosyl-L-methionine to the epsilon-amino group of 'Lys-4' of histone H3 (H3K4) via a non-processive mechanism. Part of chromatin remodeling machinery, forms H3K4me1, H3K4me2 and H3K4me3 methylation marks at active chromatin sites where transcription and DNA repair take place. Plays an essential role in regulating the transcriptional programming of multipotent hematopoietic progenitor cells and lymphoid lineage specification during hematopoiesis (By similarity).
Synonyms: KIAA1076; KMT2G; SET1B; IDDSELD
Tractability: PROTAC: its protein half-life has been measured.
Target class: Enzyme; Transferase
Gene: Protein-coding gene on chromosome 12 (121,804,009 to 121,832,656, forward strand). Ensembl gene ENSG00000139718.
Subcellular location: Nucleus; Nucleus speckle; Chromosome; Cytoplasm
Subcellular location (Human Protein Atlas): Nucleoplasm
Pathways (Reactome):
Gene expression (Transcription): Formation of WDR5-containing histone-modifying complexes; RUNX1 regulates genes involved in megakaryocyte differentiation and platelet function
Chromatin organization: PKMTs methylate histone lysines
Gene Ontology:
Molecular function: histone H3K4 methyltransferase activity; histone H3K4 monomethyltransferase activity; protein binding; histone H3 methyltransferase activity; nucleic acid binding; RNA binding
Biological process: chromatin remodeling
Cellular component: chromosome; cytoplasm; histone methyltransferase complex; nuclear speck; nucleoplasm; nucleus; Set1C/COMPASS complex
Genetic constraint (gnomAD): Loss-of-function variants: 7 observed, 120.99 expected, observed/expected ratio (o/e) 0.0579, 90% interval 0.032 to 0.11. The synonymous counts are far from expectation, so gnomAD's model fits this gene poorly and the ratio says little. Missense variants: 2,038 observed, 2,468.7 expected, observed/expected ratio (o/e) 0.83, 90% interval 0.8 to 0.86. Synonymous variants: 1,281 observed, 1,094.7 expected, observed/expected ratio (o/e) 1.17, 90% interval 1.12 to 1.23.
Gene-disease validity (ClinGen):
ClinGen rates the evidence that SETD1B causes each of these diseases.
complex neurodevelopmental disorder (autosomal dominant): Definitive. A disorder that involves more than one phenotype associated with the central nervous system, including but not limited to intellectual disability, autism, and seizures (epilepsy).
Homologues: Orthologues: chimpanzee SETD1B (99% identical), dog SETD1B (92% identical), mouse Setd1b (90% identical), rat Setd1b (90% identical), macaque SETD1B (90% identical), rabbit SETD1B (83% identical), pig SETD1B (82% identical), guinea pig SETD1B (80% identical), tropical clawed frog setd1b (56% identical), zebrafish setd1ba (47% identical), Drosophila melanogaster G9a (7% identical), Caenorhabditis elegans met-1 (6% identical), and 11 more. Paralogues in human: SETD1A (36% identical), KMT2A (20% identical), KMT2D (18% identical), KMT2C (17% identical), KMT2B (17% identical), ASH1L (9% identical), EHMT1 (8% identical), NSD1 (8% identical), EHMT2 (7% identical), NSD3 (7% identical), NSD2 (7% identical), SETDB1 (6% identical), and 7 more.
Diseases named in the same sentence as SETD1B in open-access papers:
SETD1B is named in the same sentence as 58 diseases in open-access papers, as found by Europe PMC text mining. Sharing a sentence is not in itself a finding about the gene and the disease. The quoted sentences say what the papers report.
epilepsy (7 papers, 2020 to 2026). A brain disorder characterized by episodes of abnormally increased neuronal discharge resulting in transient episodes of sensory or motor neurological dysfunction, or psychic dysfunction. "The emerging phenotype of SETD1B-associated disorder consists of global developmental delay, language delay including regression, intellectual disability, autism, and epilepsy." (PMID 34345025, 2021). "Previously alterations of SETD1B were mainly associated with myoclonic absences and predominantly refractory epilepsy." (PMID 34345025, 2021). "In the set-2(zr2012) allele, we introduced a mutation leading to the same amino acid substitution found in SETD1B/KMT2G in a case of intellectual disability linked to epilepsy and autism." (PMID 32675280, 2020). "Our data present evidence for a loss-of-function mechanism of SETD1B variants, resulting in a core clinical phenotype of global developmental delay, language delay including regression, intellectual disability, autism and other behavioral issues, and variable epilepsy phenotypes." (PMID 34345025, 2021). "Human pathogenic variants in coding regions of SETD1B have been associated with ASD, ID, and epilepsy." (PMID 36845425, 2023). "Noticeable differences between both syndromes are the incidence of epilepsy, which is more common for SETD1B (20% in SETD1A, 78% in this cohort), and the absence of a male predominance for SETD1A (9 males of 19 cases)." (PMID 34345025, 2021). "Finally, diagnostic findings in patients with syndromic vs. non-syndromic symptoms revealed a significant overlap of frequent causes of monogenic epilepsies, including SCN1A, CACNA1A, and SETD1B, confirming the heterogeneity of the associated conditions." (PMID 38125836, 2023). "Additionally, SETD1B has been identified as a candidate gene for 12q24.31 microdeletion syndrome, which presents with ID, autism-like features, facial dysmorphisms, and epilepsy." (PMID 36845425, 2023). "This indicates that SETD1B dysfunction severely impacts physiological neurodevelopment even in the absence of epilepsy, suggesting the condition is a developmental encephalopathy, with or without epilepsy." (PMID 34345025, 2021).
language delay (6 papers, 2019 to 2025). "Consistent with this, pathogenic variants in SETD1B have been associated with a syndromic intellectual developmental disorder including seizures and language delay (IDDSELD, OMIM 619000)." (PMID 34345025, 2021). "Pathogenic variants in SETD1B have been associated with a syndromic neurodevelopmental disorder including intellectual disability, language delay, and seizures." (PMID 34345025, 2021). "This patient was previously diagnosed with intellectual developmental disorder with seizures and language delay (IDDSELD; OMIM 619000), a disorder caused by SETD1B variants." (PMID 36322151, 2023). "A comparison of phenotypes of patients with a SETD1B DNAm signature showed overlapping clinical features such as intellectual disability, language delay, autism, seizures, full cheeks, and tapering fingers." (PMID 31685013, 2019).
Intellectual disability (5 papers, 2019 to 2023). "We also analysed the transcriptome of the set-2(zr2012) allele that expresses a mutant SET-2 protein with an amino acid substitution found in SETD1B in a case of intellectual disability." (PMID 32675280, 2020). "All patients with a SETD1B signature-positive methylation profile presented with an intellectual disability." (PMID 31685013, 2019).
colon cancer (4 papers, 2019 to 2022). "To further examine the prognostic value of ZEB1/SETD1B axis in colon cancer patients, we investigated a data set of 177 patients with colorectal carcinoma (GEO DataSet: GSE17536)." (PMID 32094334, 2020).
colorectal cancer (4 papers, 2020 to 2023). A primary or metastatic malignant neoplasm that affects the colon or rectum. "SETD1B has recently been identified as a putative tumor suppressor gene associated with colorectal cancer and endometrial cancer." (PMID 35058979, 2022). "It is known that mutations of SETD1B play a role in tumorigenesis of gastric and colorectal cancers with MSI35." (PMID 32094334, 2020). "SETD1B, an essential component of a histone methyltransferase complex, believed to have essential, even housekeeping, functions within cells, although playing no clear role in malignancy, has been reportedly mutated in gastric and colorectal cancers." (PMID 37444571, 2023). "The chromatin modifier SETD1B, a histone methyltransferase of Lys4 at histone H3, is a direct transcriptional target of ZEB1, which regulates the expression pattern of the SETD1B in colorectal cancer cells." (PMID 34943943, 2021). "For the first time we report that ZEB1 directly regulates the expression pattern of the histone methyltransferase SETD1B in colorectal cancer cells." (PMID 32094334, 2020). "From clinical data we extracted the worst prognosis when both, ZEB1 and SETD1B were highly expressed whereas in the low/low group nearly all colorectal cancer patients survived the first 5 years after surgery." (PMID 32094334, 2020).
developmental delay (2 papers, 2020 to 2021). "Developmental delay appeared to precede seizure onset, suggesting SETD1B dysfunction impacts physiological neurodevelopment even in the absence of epileptic activity." (PMID 34345025, 2021).
leukemia (2 papers, 2024 to 2025). A malignant (clonal) hematologic disorder, involving hematopoietic stem cells and characterized by the presence of primitive or atypical myeloid or lymphoid cells in the bone marrow and the blood. "Consistent with the mouse leukemia model, the loss of SETD1B reduced the MYC expression and broad H3K4me3 peaks at 4 days post-Dox treatment." (PMID 40341256, 2025). "Although the precise contribution of SETD1B mutations in leukemia prognosis remains unclear, these data and our study suggest the cell context-dependent role of SETD1B in hematopoiesis and leukemogenesis." (PMID 40341256, 2025). "Thus, oncogenic driver mutations that induce cytokine-independent growth in leukemia would commonly depend on the SETD1B-MYC axis." (PMID 40341256, 2025). "Genetic alterations in SETD1B have been linked to poor outcomes in patients with leukemia, including frameshift or nonsense mutations in chronic myeloid leukemia and a missense mutation in the non-catalytic region (Ala889Asp) in chronic lymphoproliferative disorder of natural killer cells." (PMID 40341256, 2025). "In our previous investigation, we reported a dispensable role of SETD1B in murine MLL-AF9 leukemia cells." (PMID 40341256, 2025). "In contrast, our results suggested that SETD1B is a bona fide H3K4me3 methyltransferase in leukemia cells." (PMID 40341256, 2025). "Our study also highlights the crucial role of SETD1B-dependent H3K4me3 breadth in the MYC pathway in leukemia." (PMID 40341256, 2025). "Our results indicate that SETD1B is an essential H3K4 methyltransferase for cytokine-independent cell proliferation in MLL-r leukemia cells." (PMID 40341256, 2025). "The SETD1B expression was significantly elevated in patients with MLL-r leukemia." (PMID 40341256, 2025). "Therefore, a thorough understanding of the role of SETD1B-mediated H3K4me3 breadth is critical for developing markers and therapies for other leukemia subtypes and cancers dependent on MYC." (PMID 40341256, 2025). "Therefore, we performed the CRISPR assay against the SET domain of MLL family genes in two other murine MLL-r leukemia models to confirm the effect of SETD1B SET domain disruption." (PMID 40341256, 2025). "We also performed ChIP-seq for SETD1B and SETD1A using HA-tagged SETD1B or SETD1A expressing MOLM-13 human MLL-r/FLT3-ITD leukemia cells." (PMID 40341256, 2025). "In conclusion, we identified the function of the catalytic domain of SETD1B in H3K4me3 breadth and cytokine-independent cell proliferation in MLL-r leukemia." (PMID 40341256, 2025). "The development of a SETD1B-specific inhibitor or an expanded application of HMT inhibitors, such as Chaetocin, which also target SETD1B, will be a valuable tool against MYC-dependent leukemia." (PMID 40341256, 2025). "SETD1B dependency was also observed in the MOLM-13 human MLL-r/FLT3-ITD leukemia cell line but not in the U937 and K562 non-MLL-r leukemia cell lines." (PMID 40341256, 2025). "Thus, a thorough understanding of SETD1B-mediated H3K4me3 breadth is critical for developing markers and therapies for MYC-dependent leukemia subtypes." (PMID 40341256, 2025). "In the syngeneic murine AML model, Setd1b sgRNA expression decreased MLL-r leukemia cell propagation in vivo, even without FLT3-ITD or NrasG12D expression; thus, SETD1B requirement increased in the in vivo environment." (PMID 40341256, 2025). "We transduced FLT3-ITD into MA9 cells and monitored their sensitivity to Setd1b sgRNA with or without cytokines to examine the effects of oncogenic signaling and cytokines on MLL-r leukemia cells." (PMID 40341256, 2025). "Furthermore, small hairpin RNA knockdown of SETd1a but not SETd1b transcripts induces differentiation and apoptosis in murine and human MLL1F-leukemia cells." (PMID 39342993, 2024).
liver cirrhosis (2 papers, 2023 to 2025). "Increased SETD1B expression in HCC positively correlated with tumor size, clinical stage, and liver cirrhosis." (PMID 37444571, 2023).
lung carcinoma (2 papers, 2017 to 2022). "We detected a peak of homozygous deletions in lung cancer close to SETD1B, a member of a family of histone methyltransferases that also includes SETD2, known to be involved in renal carcinoma." (PMID 29089486, 2017).
schizophrenia (2 papers, 2020 to 2021). A major psychotic disorder characterized by abnormalities in the perception or expression of reality. "One likely pathogenic SETD1B variant without clinical information was identified in a schizophrenia cohort, but psychosis was not reported in our SETD1B cohort." (PMID 34345025, 2021).
Achalasia (1 paper, 2021). A disorder of esophageal motility characterized by the inability of the lower esophageal sphincter to relax during swallowing and by inadequate or lacking peristalsis in the lower half of the body of the esophagus. "The two consanguineous siblings (individuals 11 and 12) share, besides the homozygous VUS in SETD1B, also homozygous VUS in NBAS (associated with immune defects) and NOS1 (associated with achalasia)." (PMID 34345025, 2021).
Anorexia (1 paper, 2020). Lack of desire to eat (loss of appetite). "Our study showed that the increased H3K4me3 modified by Setd1b could enhance the pepck mRNA expression to improve gluconeogenesis and thus inhibit the appetite of the mandarin fish with anorexia after feeding carbohydrate-rich diets." (PMID 32636801, 2020).
Burn-McKeown syndrome (1 paper, 2025). "The monogenic conditions identified included DNAH5-related primary ciliary dyskinesia, Burn-McKeown syndrome, Tatton-Brown-Rahman syndrome, SETD1B-related neurodevelopmental disorder, and SET-related disorder." (PMID 39695270, 2025).
cholangiocarcinoma (1 paper, 2025). A carcinoma that arises from the intrahepatic biliary tree (intrahepatic cholangiocarcinoma) or from the junction, or adjacent to the junction, of the right and left hepatic ducts (hilar cholangiocarcinoma). "Surprisingly, SETD1B expression was most significantly elevated in hepatocellular carcinoma (HCC, referred to as LIHC in TCGA) and cholangiocarcinoma (CHOL)." (PMID 40860182, 2025).
Down syndrome (1 paper, 2012). "We report here that Setd1b interacts specifically with both Rbm15 and the leukemogenic Rbm15-Mkl1 fusion protein that is frequently found in non-Down syndrome pediatric AMKL." (PMID 22927943, 2012).
Ewing sarcoma (1 paper, 2017). A small round cell tumor that lacks morphologic, immunohistochemical, and electron microscopic evidence of neuroectodermal differentiation. "Both MLL1 (KMT2A) and SETD1B (KMT2G) are highly expressed by Ewing sarcoma cell lines, with expression levels comparable to those of several hematological malignancies known to be driven by MLL rearrangements and/or amplification." (PMID 27888797, 2017).
glioblastoma (1 paper, 2023). The most malignant astrocytic tumor (WHO grade IV). "Mass spectrometry analysis revealed the interaction partners of ASH2L in glioblastoma cell lines as SET1/MLL family members including SETD1A, SETD1B, MLL1 and MLL2." (PMID 37974198, 2023). "To address the essential role of ASH2L for glioblastoma cell survival further, we focused our attention to chromatin modifying complexes, specifically, SET1/MLL family of histone methyltransferases SET1 (SETD1A), SET1B (SETD1B), MLL1 (KMT2A), MLL2 (KMT2B), MLL3 (KMT2C) and MLL4 (KMT2D)." (PMID 37974198, 2023).
liver cancer (1 paper, 2025). An epithelial or non-epithelial malignant neoplasm that arises from the liver. "Here, we report that the methyltransferase SETD1B plays a crucial role in the development of HCC by contributing to the stemness of liver cancer stem cells (LCSCs)." (PMID 40860182, 2025). "To investigate the role of SETD1B in liver cancer, we assessed its expression characteristics using TCGA database." (PMID 40860182, 2025).
malaria (1 paper, 2025). Malaria is a serious and sometimes fatal disease caused by a parasite that commonly infects a certain type of mosquito which feeds on humans. "Another blast match to this same transcript, Histone‐lysine N‐methyltransferase (SETD1B), was differentially expressed in 'amakihi succumbing to experimentally infected malaria, relative to control birds." (PMID 40909016, 2025).
male infertility (1 paper, 2025). The inability of the male to effect fertilization of an ovum after a specified period of unprotected intercourse. "Inactivation of Setd1b resulted in Pol II redistribution from broad H3K4me3 domains to regular H3K4me3 regions, consequently, disrupting the expression output and timing of genes essential for spermatid development, leading to impaired spermiogenesis and consequent male infertility." (PMID 40033033, 2025).
myelodysplastic syndrome (1 paper, 2018). A clonal hematopoietic disorder characterized by dysplasia and ineffective hematopoiesis in one or more of the hematopoietic cell lines. "Except for one case study of polycythemia vera, no SETD1B mutations in human hematologic malignancies such as myeloproliferative neoplasm (MPN), myelodysplastic syndrome (MDS), and AML have been reported so far." (PMID 29916805, 2018).
Neurodevelopmental delay (1 paper, 2023). "Pathogenic variants in SETD1A have been reported in association with early onset epilepsy, neurodevelopmental delay and an increased risk of schizophrenia (MIM:618832; MIM:619056), and variants in SETD1B (MIM:619000), SETD2 and SETD5 (MIM:616761) have also been associated with NDDs." (PMID 37166351, 2023).
prostate carcinoma (1 paper, 2023). A carcinoma that arises from epithelial cells of the prostate gland. "Biased towards African-specific drivers (63 versus 9 shared), many are novel to prostate cancer (18/63), including several putative therapeutic targets (CHD7, DPF3, POLR1B, SETD1B, UBTF, and VPS72)." (PMID 37444571, 2023).
Sotos syndrome (1 paper, 2021). Sotos syndrome is a rare multisystemic genetic disorder characterized by a typical facial appearance, overgrowth of the body in early life with macrocephaly, and mild to severe intellectual disability. "For example, while SETD1B variants in the SETD1B-related syndrome result in a strong hypermethylated signature, NSD1 variants associated with Sotos syndrome display remarkable hypomethylation." (PMID 33337535, 2021).
Splenomegaly (1 paper, 2018). Abnormal increased size of the spleen. "Irrespective of the KO strategy, we observed several common hallmark features associated with Setd1b-deficient hematopoiesis, including peripheral thrombo- and lymphocytopenia, multilineage dysplasia, and varying degrees of splenomegaly caused by myeloid-biased extramedullary hematopoiesis." (PMID 29916805, 2018).
Thrombocytopenia (1 paper, 2018). A reduction in the number of circulating thrombocytes. "In summary, the confined deletion of Setd1b within the hematopoietic system of cKO transplanted mice was sufficient to generate major characteristics of the cKO phenotype (lympho- and thrombocytopenia, dysplasia, myeloid skewing in spleen, disturbed HSPC homeostasis)." (PMID 29916805, 2018).
viral infections (1 paper, 2020). "We confirmed variants with putative driver role of MAP10, MPZL1, RPS6KA1, SETD1B, TAOK2, TMEM127, and TNFRSF1A genes, and of genes linked to viral infections (DDX3X and RSF1) and DNA repair (PAXIP1)." (PMID 32321919, 2020).